RET (ret proto-oncogene)
Diseases named in the same sentence as RET in open-access papers (continued):
Sharing a sentence is not in itself a finding about the gene and the disease.
neuritis (1 paper, 2026). A neuropathy arising from inflammation of one or more nerves. "Moreover, CCL2 can attract CCR2‐positive macrophages to the immune microenvironment of neuritis, where they promote neural invasion by activating RET signaling in cancer cells." (PMID 41556039, 2026).
neuroepithelial tumors (1 paper, 2026). "This case illustrates the diagnostic and therapeutic challenges posed by rare, highly aggressive CNS neoplasms that do not map to a WHO-defined entity on available testing and highlights the potential clinical relevance of identifying actionable RET fusions in high-grade neuroepithelial tumors." (PMID 42027864, 2026).
non-small cell lung adenocarcinoma (1 paper, 2022). Type of epithelial lung cancer arising from glandular origin. "RET gene positivity in non-small cell lung adenocarcinoma is approximately 1% to 2%, RET fusion mutations and some other genetic mutations (eg, EGFR receptor mutations, ALK gene rearrangements) are mutually exclusive." (PMID 36582799, 2022).
ovarian serous carcinoma (1 paper, 2017). "RET tyrosine kinase is a fusion partner of TRIM27 (tripartite motif-containing 27), which is highly expressed in normal epithelial cells of the ovary and fallopian tube and in ovarian serous carcinoma cells." (PMID 28871116, 2017).
ovarian tumor (1 paper, 2020). "Local sequencing analysis of a biopsy from the primary ovarian tumor collected 2.5 months prior to the study start, approximately 3 weeks before cessation of letrozole therapy, revealed the presence of RET and TrkA (NTRK1) protocol-defined mutations." (PMID 32292573, 2020).
papilloma (1 paper, 2025). A benign epithelial neoplasm that projects above the surrounding epithelial surface and consists of villous or arborescent outgrowths of fibrovascular stroma. "Mild epithelial dysplasia and papillomas with foci os pseudoepitheliomatous hyperplasia were noted in B[a]P (66.6%) and RET 40 μM (83.3%)." (PMID 40211435, 2025).
PEComas (1 paper, 2025). "PEComas with TSC1/2 mutations or TFE3 rearrangements respond to mTORC1 inhibition, while IMTs harboring ALK, RET, PDGFRB, or NTRK rearrangements demonstrate marked responses to ALK or TRK inhibitors." (PMID 41463261, 2025).
pituitary (1 paper, 2021). "Lack of AIP or pathogenic mutations block this pathway promoting the RET-survival pathway characteristic of the pituitary somatotrophinomas." (PMID 34588620, 2021).
polycystic kidney disease (1 paper, 2020). A usually autosomal dominant and less frequently autosomal recessive genetic disorder characterized by the presence of numerous cysts in the kidneys leading to end-stage renal failure. "Genetic abnormalities such as autosomal dominant or recessive inheritance of polycystic kidney disease, hereditary kidney dysplasia, caused by RET and UPK3A gene mutations and chromosomal abnormalities, can result in developmental abnormalities and lead to Potter sequence." (PMID 32347825, 2020).
prostate tumors (1 paper, 2018). "RET and GFL expression have been implicated in metastasis or invasion in diverse human cancers including breast, pancreatic, and prostate tumors, where they are linked to poorer patient prognosis." (PMID 30666215, 2018). "RET protein has been detected in 20–75% of high grade prostate adenocarcinomas (Gleason score >3) while GDNF is upregulated in both prostate tumors and surrounding stroma." (PMID 30666215, 2018).
psychostimulant addiction (1 paper, 2023). "As a potent neurotrophic factor modulating the function of dopamine neurons, glial cell line-derived neurotrophic factor (GDNF) acting through its receptor RET on dopamine neurons may provide a novel therapeutic avenue towards psychostimulant addiction." (PMID 37238631, 2023). "Constitutively active RET has been shown to strongly prolong CPP extinction to amphetamine, suggesting that RET inhibition might be a plausible mechanism to facilitate the extinction of psychostimulant addiction." (PMID 37238631, 2023).
renal hypoplasia (1 paper, 2017). Renal hypoplasia is a developmental anomaly in which one or both kidneys (unilateral or bilateral renal hypoplasia, respectively) have a deficit in the number of nephrons and may be small. "Similarly, while common hypomorphic variants of RET or PAX2 have been associated with subtle renal hypoplasia, their inactivation has been shown to result in severe renal malformations." (PMID 29240767, 2017).
Renal insufficiency (1 paper, 2022). A reduction in the level of performance of the kidneys in areas of function comprising the concentration of urine, removal of wastes, the maintenance of electrolyte balance, homeostasis of blood pressure, and calcium metabolism. "Due to renal insufficiency, she subsequently received pralsetinib with gradually reduced dosages (400 mg-300 mg-200 mg-100 mg qd) and achieved a partial response (PR) lasting for more than 10 months, accompanied by the declined allele frequencies of all 3 RET fusions." (PMID 36451418, 2022).
seminoma (1 paper, 2012). A radiosensitive malignant germ cell tumor found in the testis (especially undescended), and extragonadal sites (anterior mediastinum and pineal gland). "On the other hand hyperactivation of RET in Ret+/+ mice by overexpressing glial derived neurotrophic factor (GDNF), the major ligand of RET in the testis, results in germ cell tumors that are seminoma-like and led to disruption of normal spermatogenesis." (PMID 22359510, 2012).
sigmoid colon cancer (1 paper, 2022). A malignant neoplasm involving the sigmoid colon. "Ishizaka and colleagues identified a second form of activated RET, ret-II, in human sigmoid colon cancer, which lacked the coding region for the transmembrane domain found in wild-type RET." (PMID 35957881, 2022).
somatotropinomas (1 paper, 2024). "Alongside the fact that the patient's father and daughter carried the same variant, we investigated the clinical significance of this variant in the context of somatotropinomas and other endocrine tumors, reviewing the RET mutations' oncogenic mechanisms." (PMID 38339173, 2024).
stomatitis (1 paper, 2023). Inflammation of the oral mucosa due to local or systemic factors. "Selective RET inhibitors cause a lower incidence of stomatitis compared with cabozantinib and vandetanib, so the clinical relevance and drug discontinuation because of stomatitis are less common with selpercatinib and pralsetinib." (PMID 38118420, 2023).
tauopathy (1 paper, 2021). Neurodegenerative disorders involving deposition of abnormal tau protein isoforms (tau proteins) in neurons and glial cells in the brain. "Our work in Drosophila identified whole body pro-targets and anti-targets for RET-associated cancer and Tauopathy." (PMID 34520464, 2021). "In this challenge, we challenged participants to predict single chemical entities that target pro-targets but avoid anti-targets for two unrelated diseases: RET-based tumors and an inherited form of Tauopathy." (PMID 34520464, 2021).
thoracic tumors (1 paper, 2017). "We harvested the thoracic tumors of these mice and assessed the extent of RET phosphorylation by western blot." (PMID 29088743, 2017). "Although there were individual differences, alectinib treatment tended to inhibit phosphorylation of RET and ERK in thoracic tumors." (PMID 29088743, 2017).
Thromboembolism (1 paper, 2025). The formation of a blood clot inside a blood vessel that subsequently travels through the blood stream from the site where it formed to another location in the body, generally leading to vascular occlusion at the distant site. "A retrospective analysis found that the incidence of TEs in patients with RET fusions was as high as 48%, suggesting that, like ALK and ROS1, RET may also be associated with an increased risk of thromboembolism." (PMID 40751559, 2025).
viral infection (1 paper, 2020). "Therefore, although macrophages constitutively express GFRα2, the signalling component, RET, is induced by stimuli associated with viral infection." (PMID 33020210, 2020). "We determined that viral infection, or mimics thereof, specifically enhanced the production of the GFRα2 ligand, NRTN, from lung epithelium, whereas type I IFNs induced expression of the signalling receptor RET in lung macrophages." (PMID 33020210, 2020).
tumor (961 papers, 1993 to 2026). "Variant allele frequency (VAF) analysis demonstrated a significant positive correlation between driver mutation burden and tumor size in both RET- and RAS-mutant tumors, supporting the clonal contribution of these alterations." (PMID 42125600, 2026). "Since then, additional agents have secured tumor-agnostic FDA indications, including targeted therapies for NTRK gene fusions, BRAF V600E mutations, RET fusions, as well as treatments based on high tumor mutational burden (TMB-H) or HER2 overexpression." (PMID 41228293, 2025). "RET fusion-positive NSCLC mostly present as an “immune cold” phenotype with low tumor mutational burden, low PD-L1 expression, and limited immune cells." (PMID 41018100, 2025). "The same mutation of the RET gene (chr10:43609933, c.1886_1891delTGTGCG, p.Leu629_Asp631delinsHis, coverage: 1983, allele frequency: 48.32%) that was found in the primary tumour tissue was detected in the present sample." (PMID 40729029, 2025). "When evaluating the pathogenic mutations of DM, a match can also be found in the RET protooncogene compared to the primary tumour tissue and the LNM." (PMID 40729029, 2025). "RET alterations are best identified using massively parallel DNA and RNA sequencing from tumour samples, which can detect RET small variants or rearrangements in a histotype-agnostic manner." (PMID 40138217, 2025). "In patients with germline wild-type RET status, tumor tissue should be tested for somatic RET mutations at the time of diagnosis only if they present with high-risk clinical or pathological features." (PMID 40540622, 2025). "Consistent with our prior observations, two of the six tumor cases exhibited concurrent MAPK pathway alterations: one carried a CCDC186::RET fusion, while the other had a KRAS p.G12V point mutation." (PMID 41573641, 2025). "Recently, the importance of the tumor microenvironment has also been investigated in cancers associated with the RET oncogene." (PMID 40282539, 2025). "The oncogenic signaling pathway mutations consisted of KRAS, EGFR, and ALK/ROS1/RET mutations, which play crucial roles in cell proliferation and are associated with tumor aggressiveness and a higher risk of recurrence." (PMID 40507370, 2025). "We compared tumor mutation burden (TMB) in NTRK+/RET+ CRC with all other NTRK+ and RET+ solid tumors using the American Association for Cancer Research (AACR) GENIE database (Version 13.0)." (PMID 39950716, 2025). "Following the detection of the RET M918T mutation, treatment was switched to selpercatinib, and rapid tumor response and endocrine symptom resolution were observed." (PMID 40747199, 2025). "Cabozantinib is a multi-kinase inhibitor that targets MET, VEGFR, RET, and other tumor-associated tyrosine kinases involved in tumor growth and angiogenesis." (PMID 40850949, 2025). "Marked tumor reduction was achieved with selpercatinib, suggesting the oncogenic relevance of the RET A641R mutation in MTC." (PMID 40638225, 2025). "These include NTRK fusions, BRAF V600E mutations, RET fusions, Her-2 positive status, high tumor mutational burden (TMB-H), and deficient mismatch repair/high microsatellite instability (dMMR/MSI-H)." (PMID 40868288, 2025). "In these patients, RET/PTC mutations are often linked to more aggressive tumor behavior and an increased frequency of metastatic dissemination." (PMID 40507982, 2025). "Redifferentiation has been used in patients with BRAF-mutated and RAS-mutated tumours in prospective trials and in the case of patients with RET or NTRK fusions." (PMID 40318680, 2025). "Preclinical studies demonstrated nanomolar effectivity against diverse RET alterations, including V804 resistance mutations, with strong anti-tumour activity, even in brain metastases." (PMID 40332222, 2025). "The rapid tumor response to selpercatinib and normalization of endocrine abnormalities highlight the clinical value of early calcitonin measurement and RET mutation analysis in CUP with neuroendocrine features." (PMID 40747199, 2025).
tumor (continued). "Oncogenic activation of RET kinase through fusion or mutation drives tumor cell proliferation and survival, establishing it as both a diagnostic marker and therapeutic target across multiple cancers." (PMID 41181595, 2025). "Somatic RET mutations occur in up to 60% of sMTC cases and are associated with tumour aggressiveness, and M918T (40%) is the most common RET alteration, along with small deletions and insertions." (PMID 40332222, 2025). "This case also highlights the anti-tumor effect of selpercatinib in patients with RET transmembrane domain mutations." (PMID 40638225, 2025). "The loss of the mutated gene is to be assumed here, as the frequency of the RET protooncogene also decreases from the primary tumour via LNM and DM." (PMID 40729029, 2025). "Somatic RET mutations, particularly the p.Met918Thr (M918T) variant, have been repeatedly associated with an unfavorable prognosis, including advanced tumor stage, higher T category, and increased rates of lymph node and distant metastases." (PMID 41514606, 2025). "The presence of RET fusions in PTC cases is associated with more aggressive tumour behaviour, with high rates of local lymph node and distant metastasis." (PMID 40138217, 2025). "Approximately 2 % of human cancers exhibit alterations in the receptor tyrosine kinase gene RET, including point mutations or fusions that increase kinase activity and promote tumor cell growth." (PMID 39166093, 2024). "An analysis of SCLC primary tumor samples using a panel of oncogenic mutations has identified an activating M918T RET somatic mutation." (PMID 38473324, 2024). "Here, we explore the potential risk of developing other MAPK-driven neoplasms secondary to the activation of mutations downstream of selective RET inhibition." (PMID 38804700, 2024). "NCCN also suggests biomarker-guided treatments for tumor mutation burden-high and RET fusion-positive tumors, and ESMO suggests treatment for patients with BRCA1/2 or PALB2 mutations." (PMID 38838500, 2024). "Previous reports examining the clinicopathologic characteristics of somatic RET mutations in sMTC found that RET-mutated sMTC was associated with increased tumor size, nodal and distant metastases, and decreased OS." (PMID 38660141, 2024). "Early diagnosis is possible by determining the tumour marker calcitonin (Ctn) when clarifying nodular goitre and by detecting the mutation in the proto-oncogene RET in the MEN2 families." (PMID 38919477, 2024). "RET rearrangements or mutations determine aberrant activation of its catalytic activity, contributing to tumor formation and progression." (PMID 39211557, 2024). "A mutation in the RET gene, usually M918 T, is often detectable in the tumour tissue of sporadic MTC." (PMID 38919477, 2024). "Otherwise, the majority of NSCLC patients harboring RET fusions exhibit low levels of PD-L1 expression and tumor mutation burden, resulting in suboptimal responses to immune checkpoint inhibitors." (PMID 39372862, 2024). "Mutations of the RET gene cause abnormal RET expression, subsequently initiating and advancing tumour development." (PMID 38738791, 2024). "The identification of RET splice variants in MTC represents a distinguishing genetic diagnostic feature of this tumor and provides an opportunity for a better understanding MTC pathogenesis." (PMID 38566816, 2024). "In sporadic disease, somatic pathogenic RET variants drive approximately half of cases, with rat sarcoma virus (RAS) mutations driving 70% of RET wild-type tumours." (PMID 39001359, 2024). "Selpercatinib selectively inhibits activated RET, thereby inhibiting tumor growth, and it has demonstrated high efficacy and safety in patients with RET mutation-positive MTC in the LIBRETTO-001 trial." (PMID 38647958, 2024). "Mechanistically, RET rearrangement has been shown to lower tumor mutation burden and PD‐L1 expression, explaining their hyporesponsiveness to ICIs." (PMID 38349001, 2024).